TNF (tumor necrosis factor)
Diseases named in the same sentence as TNF in open-access papers (continued):
Sharing a sentence is not in itself a finding about the gene and the disease.
vitamin D deficiency (108 papers, 2012 to 2026). A nutritional condition produced by a deficiency of VITAMIN D in the diet, insufficient production of vitamin D in the skin, inadequate absorption of vitamin D from the diet, or abnormal conversion of vitamin D to its bioactive metabolites. "Patients with vitamin D deficiency exhibited significantly higher IL-6 and TNF-α levels and worse WOMAC scores.Data shows that vitamin D deficiency is associated with increased inflammation and poorer functional outcomes in knee OA." (PMID 41170094, 2025). "For instance, vitamin D deficiency removes the anti-inflammatory brake, leading to higher levels of IL-6 and TNF-α and accelerating renal injury." (PMID 41142318, 2025). "Vitamin D deficiency has been linked to enhanced expression of proinflammatory interleukins such as IL-1β, IL-6, and TNF-α, which are physiological mediators of the inflammatory response and are frequently elevated in the tears of DES patients." (PMID 41157226, 2025). "Vitamin D deficiency inhibits osteoblast differentiation and releases inflammatory factors (TNF-α and IL-6), leading to impaired callus formation and accelerated osteolysis around internal fixation." (PMID 40730978, 2025). "Patients receiving anti-TNF or other biologic agents have been shown to exhibit a higher prevalence of vitamin D deficiency, whereas vitamin D deficiency has been linked to poor response to induction therapy." (PMID 41373989, 2025). "Vitamin D deficiency is associated with elevated inflammatory cytokines (IL-6 and TNF-α) and worse clinical outcomes in kneeosteoarthritis." (PMID 41170094, 2025). "In in vitro trophoblast experiments, vitamin D deficiency decreased the expression of hCG and increased the expression of tumor necrosis factor-alpha, interleukin-6, and interferon-gamma, thereby increasing the T-helper/T-cytotoxic cell ratio." (PMID 41367918, 2025). "Patients in the high-NRCD group exhibited elevated pro-inflammatory cytokine (IL-12 and TNFα) levels alongside pronounced vitamin D deficiency." (PMID 40476734, 2025). "Although with a higher prevalence of vitamin D deficiency, up-regulation of miR-346 and TNF-α and down-regulation of vitamin D receptor were reported to be responsible for the induction of apoptosis in oral mucosal keratinocytes in OLP patients." (PMID 38907640, 2024). "Vitamin D deficiency leads to diminished production of inflammatory cytokines, including IL-1, IL-6, IL-12, IL-21, and TNF-α, while enhancing the production of anti-inflammatory cytokines, such as IL-10." (PMID 39598148, 2024). "Vitamin D deficiency also potentiates proinflammatory cytokines, including Tumor necrosis factor (TNF), type 1 interferons (IFN), and IL-6." (PMID 39139171, 2024). "In a study conducted to consider the immunomodulatory properties of vitamin D, it was found that the TNF-α levels were normal and the IL-10 levels were low in CD patients with vitamin D deficiency." (PMID 38623153, 2024). "Pro-inflammatory adipokines IL-6 and TNF-α are produced and released when vitamin D deficiency occurs, resulting in an increase in the amount of fat in the body." (PMID 36360622, 2022). "The higher levels of PTH as a compensatory mechanism of vitamin D deficiency in diabetic patients can stimulate inflammatory cytokines like tumor necrosis factor (TNF)-α and interleukin (IL)-6 that have important roles in the pathogenesis of DR." (PMID 35778716, 2022). "Vitamin D deficiency has been associated with elevated systemic proinflammatory cytokines in pregnancy and at delivery (IL-6 and TNF-α) and low birth weight." (PMID 34836049, 2021). "The multivariate logistic analysis showed that severe vitamin D deficiency, IL-6, and TNF-α were independent risks for painful DPN after adjusting for confounding factors." (PMID 33777989, 2021).
vitamin D deficiency (continued). "The results of this study revealed that vitamin D deficiency is associated with an increased expression of IL-33, IL-37, IL-6, TNF-α, TLRs, DAMPs, and MMPs, while vitamin D supplementation is associated with a decreased expression of the former." (PMID 34842603, 2021). "For some autoimmune conditions, vitamin D deficiency has also been related to high levels of pro-inflammatory cytokines, such as TNF-α and IFN-γ." (PMID 34071293, 2021). "By detecting liver inflammation level, we found that IL-1β, IL-6and TNF-α were significantly elevated in livers and pancreas of the offspring in the vitamin D deficiency group compared to control group at all time points." (PMID 32184720, 2020). "Vitamin D deficiency shifts this system toward a pro-inflammatory state that favors Th1 and Th17 activation and increased expression of TNF, IFNγ, and IL-17, as well as elevated expression of pro-inflammatory Il-4, IL-5 and IL-13, and gut barrier dysfunction." (PMID 32093192, 2020). "On the other hand, it is known that vitamin D deficiency is associated with a pro-inflammatory profile (IL-1, IL-2, IL-6, or TNF-α) which is modulated by calcitriol." (PMID 31068933, 2019). "Vitamin D deficiency was correlated with TNF-α serum levels, possibly increasing the susceptibility of older adults to a proinflammatory state and its related diseases." (PMID 29104377, 2017). "In univariate logistic regression models, higher levels of D-dimer, IL-6, and TNF-α were also associated with vitamin D deficiency." (PMID 28464004, 2017). "Vitamin D deficiency, also known as hypovitaminosis D, is positively associated with serum levels of inflammatory markers, such as IL-6, TNFα and C-reactive protein in obese participants." (PMID 28353634, 2017). "In univariate analysis, we demonstrated an association of D-dimer, IL-6 and TNF-α with vitamin D deficiency, suggesting a relationship between vitamin D and inflammation." (PMID 28464004, 2017). "This variation is independent from 25(OH)D concentrations, except for TNF-α, the levels of which are exacerbated in patients with vitamin D deficiency." (PMID 29104377, 2017). "In UC patients, presence of the A-allele was associated with enhanced use of anti-TNF medication and reduced prevalence of malabsorption syndrome, but at the same time—and in line with more severe disease—vitamin D deficiency was more common in those patients." (PMID 27467733, 2016). "In females, a significant inverse association exists between 25(OH)D and TNF-α, whereby vitamin D deficiency increases levels of the inflammatory cytokine." (PMID 26020962, 2015). "On the contrary, vitamin D deficiency is associated with high level of inflammatory factors such as IL-6, TNF-α, and C-reactive protein (CRP)." (PMID 25741510, 2015). "Expression of VDR and TNF-α and the effect of vitamin D deficiency in post-angioplasty coronary arteries were analyzed by immunohistochemistry and histomorphometry." (PMID 22880111, 2012). "Chronic elevations in PTH due to vitamin D deficiency may contribute to bone loss through pro-inflammatory pathways involving Th17 cells, TNF-α, and IL-17." (PMID 41301518, 2025). "Urinary albumin excretion (127.05 to 104.81 μg/mg, p < 0.05), urine MCP-1/creatinine (99.38 to 89.57 ng/mmol, p < 0.05), urine TGF-β/creatinine (79 to 72.33 ng/mmol, p < 0.05), TNF-α (57.7 to 47.09 pg/mL, p < 0.05), IL-6 (44.04 to 39.88 pg/mL, p < 0.05) in vitamin D insufficiency/deficiency group." (PMID 40134933, 2025). "Moreover, vitamin D deficiency is associated with immune system dysregulation and chronic inflammatory responses, promoting elevated levels of inflammatory mediators such as TNF-α, IL-1, and prostaglandin D2, which are closely linked to sleep regulation." (PMID 40290660, 2025). "Vitamin D deficiency causes increased levels of oxidative stress by stimulating the production of proinflammatory cytokines such as interleukin-8 (IL-8) and tumor necrosis factor alpha (TNF-α)." (PMID 40507108, 2025).
vitamin D deficiency (continued). "In particular, vitamin D deficiency may promote the production of pro-inflammatory cytokines such as interleukin-6 (IL-6) and tumor necrosis factor-alpha (TNF-α), leading to impaired kidney function and subsequent uric acid accumulation." (PMID 40805984, 2025). "Moreover, vitamin D deficiency has been linked to increased production of inflammatory mediators, including IL-6 and TNF-α, further exacerbating OA progression." (PMID 40584103, 2025). "Moreover, OA patients with vitamin D deficiency showed significantly higher levels of TNF-α and IL-6 (p < 0.05, Mann−Whitney test)." (PMID 39940305, 2025). "Our findings suggest that TNF-α and IL-6 may be key mediators linking vitamin D deficiency to OA severity in older adults." (PMID 39940305, 2025). "Various inflammatory diseases have been associated with vitamin D deficiency and a study suggested that vitamin D inhibits monocyte pro-inflammatory cytokines like TNF-alpha and IFN-gamma induction by increasing the production of anti-inflammatory cytokine like IL10." (PMID 38439034, 2024). "Overall, our results suggest that dysregulated TNF-alpha signaling either in the setting of vitamin D deficiency or vitamin D hyporesponsiveness, could be important for determining MS pathogenesis." (PMID 38228657, 2024). "The TNF production in peritoneal cells stimulated with M. leprae was also lower in the vitamin D supplementation condition compared to the standard diet (p = 0.0007) and vitamin D deficiency (p < 0.001)." (PMID 39166620, 2024). "The presence of the rs11568820 polymorphic variant in the promoter region of vitamin D and vitamin D deficiency could be considered to eventually guide treatment towards drugs with a different mechanism of action compared to anti-TNF agents." (PMID 38397223, 2024). "The role of inflammation in suppressing the vitamin D status, is also possibly related to a shift in the oxidative and anti-oxidative balance and over-secretion of inflammatory mediators such as TNF-α interfering with production of 25(OH)D3 resulting in vitamin D deficiency." (PMID 39020290, 2024). "Changes in cytokines (such as interleukin-1, interleukin-6, and tumor necrosis factor-α), adipokines (such as leptin and adiponectin), and calcium and vitamin D deficiency may also play a role in bone metabolism changes during weight loss." (PMID 39770498, 2024). "Vitamin D deficiency may also intensify immune and inflammatory responses by elevating pro-inflammatory cytokines, such as IL-6 and TNF-α, which are associated with disrupted sleep patterns and poor sleep quality." (PMID 39619283, 2024). "A state when vitamin D deficiency may lead to the pro-inflammatory stage that is upregulated and thus causes an increase in TNF-α." (PMID 37885557, 2023). "Severe vitamin D deficiency associated with increased TNF-α and IL-6 levels in painful DPN group." (PMID 38179375, 2023). "Based on the present study high levels of TNF-α and IL-6 as well as vitamin D deficiency in studied participants could disturb the MMP-9/TIMP-1 balance and lipid metabolism, leading to plaque formation/ rupture in predisposed CAD patients." (PMID 38357561, 2023). "For example, vitamin D deficiency may enhance inflammation, chemokine production via NF-ƘB, parenchymal degradation, TNF-α, IL-18, histone acetylation, corticosteroid resistance, and matrix metalloproteinase (MMP)-9 production." (PMID 37006939, 2023). "The present study suggested that high levels of TNF-α and IL-6 and vitamin D deficiency in our studied patients could disturb the MMP-9/TIMP-1 balance and lipid metabolism, leading to plaque formation/ rupture in predisposed CAD patients." (PMID 38357561, 2023). "Notably, a severe vitamin D deficiency has been found associated with increased expression of inflammatory cytokines, particularly interleukin-6 and tumor necrosis factor-α, both previously reported to increase the risk of DSPN." (PMID 35474356, 2022).
vitamin D deficiency (continued). "Two mechanisms would explain the increase in MPV in the patient with vitamin D deficiency: endothelial dysfunction and the inflammatory state induced by vitamin D deficiency expressed as an increase in pro-inflammatory cytokines such as IL-6 and TNFα." (PMID 32759752, 2020). "Clinical and animal studies have suggested that vitamin D deficiency may be associated with increased circulating IL-1β and TNFα as well as with increased fibroblast proliferative activity." (PMID 30273386, 2018). "But vitamin D deficiency is associated with an exacerbation of Th1 immune response, resulting in the upregulation of the expression and production of several proinflammatory cytokines including TNF-α, IL-1β, IL-6, and IL-8, too." (PMID 29200598, 2017). "TNF-α levels were exacerbated in subjects with vitamin D deficiency." (PMID 29104377, 2017). "The available data suggest that poor nutritional status and vitamin D deficiency might be associated with increased levels of proinflammatory factors, such as TNF-α, IL-6, and CRP." (PMID 27274758, 2016). "Beside the genetic factors predisposing to AS, the prevalence of decreased BMD in (early) AS is also influenced by differences in environmental (risk) factors among countries, i.e., vitamin D deficiency, smoking, low body mass index, use of corticosteroids, and anti-TNF alpha therapy." (PMID 22706444, 2012). "Additionally, we sought to determine whether TNF-α and IL-6 could play a role as mediators of the detrimental effects of vitamin D deficiency in knee and hip osteoarthritis." (PMID 39940305, 2025). "It has been reported that vitamin D deficiency reduces the downregulation of nuclear factor-κB activity, subsequently leading to a pro-inflammatory state, with an increase in pro-inflammatory cytokines IL-6 and TNF-α and a decrease in anti-inflammatory cytokine IL-10." (PMID 39544568, 2024). "Thus, in patients with vitamin D deficiency, the combined effect of elevated TNF-α and IL-6 levels and increased release of adhesion molecules could lead to a further increase in PLT activation and aggregation." (PMID 34576172, 2021). "Several cohort studies identified risk factors for vitamin D deficiency including diagnosis of CD vs. UC, disease activity, disease duration, gender, non-Caucasian ethnicity, smoking, body mass index [BMI] and concomitant medications, in particular therapy with TNF inhibitors." (PMID 31120977, 2019). "Vitamin D deficiency is a significant correlate of albuminuria in T2D patients, independent of eGFR and basic inflammatory markers including hs‐CRP and TNF‐α." (PMID 40804707, 2025). "Vitamin D deficiency is associated with increased inflammation and it has been shown that vitamin D3 supplementation can inhibit the release of CRP, TNF-α, and IL-6." (PMID 40364117, 2025). "It is noteworthy that elevated levels of inflammatory biomarkers, such as interleukin-6 (IL-6) and tumor necrosis factor alpha (TNF-α), have been observed in patients with both knee osteoarthritis (KOA) and vitamin D deficiency." (PMID 39940305, 2025). "Blockade of TNF-α and IFN-γ significantly ameliorated these outcomes, untangling a novel mechanism underlying the association between vitamin D deficiency and adverse outcomes in CNS injury." (PMID 41334334, 2025). "Studies have shown that vitamin D deficiency is associated with elevated levels of CRP, IL-6, TNF-α, and MDA and lower levels of TAC, in newly diagnosed T2DM." (PMID 39544568, 2024). "Considering the research background, patients with IBD with vitamin D insufficiency had shorter durability for the biological treatment with TNF-α inhibitors." (PMID 36579586, 2022). "The mean serum concentrations of leptin (P = 0.002), resistin (P = 0.037), and TNF-α (P < 0.001) were significantly higher in the cases with vitamin D insufficiency (cases) than those with vitamin D sufficiency (controls)." (PMID 36071429, 2022).
vitamin D deficiency (continued). "The univariable analysis showed that severe vitamin D deficiency, being male and HbA1c, TG, LDL-C, UACR, IL-6, and TNF-α levels were significantly associated with the risk of painful DPN." (PMID 33777989, 2021). "In conclusion, severe vitamin D deficiency plays a role in painful DPN pathogenesis through elevated inflammation IL-6 and TNF-α levels." (PMID 33777989, 2021). "Elevated TNF-α, INF-γ, IL-1β, and IL-2 levels have been observed in patients with vitamin D deficiency." (PMID 34281061, 2021). "Vitamin D can significantly reduce AGEs and TNF-α serum levels and gene expression of RAGE in PBMCs of T2DM patients with vitamin D deficiency or insufficiency (serum levels of 25(OH) vitamin D3 < 30 ng/mL)." (PMID 31673295, 2019). "Here, we investigated the expression of TNF-α and VDR in post-angioplasty coronary artery neointimal lesions of hypercholesterolemic swine and examined the effect of vitamin D deficiency on the development of coronary restenosis." (PMID 22880111, 2012). "The evidence from this study suggested that there is a strong association between vitamin D deficiency and albuminuria in T2D patients, irrespective of both the eGFR and inflammatory marker levels, such as the serum TNF‐α and hs‐CRP levels." (PMID 40804707, 2025). "Vitamin D deficiency is a significant correlate of albuminuria in T2D patients, independent of glomerular filtration rate (GFR) and basic inflammatory markers including hs‐CRP and TNF‐α." (PMID 40804707, 2025). "The results of the study confirmed a constructive association between vitamin D deficiency and IL 10 and a negative correlation between vitamin D deficiency, TNF-alpha, and IFN-gamma." (PMID 38439034, 2024). "We found a higher prevalence of hypovitaminosis D in HAM/TSP patients than in controls and AC and a significant association between vitamin D deficiency and higher levels of TNF-α in HAM/TSP patients, but not in AC." (PMID 34835029, 2021). "Severe vitamin D deficiency status may play a role in the painful DPN pathogenesis through elevated IL-6 and TNF-α levels." (PMID 33777989, 2021). "We found that the inflammatory markers, comprising hs-CRP and inflammatory cytokines (IL-1 beta, IL-6, and TNF-alpha), were similar between hemodialysis patients with and without vitamin D deficiency." (PMID 32371900, 2020). "Concomitant medical therapies (e.g. corticosteroids, thiopurines or biologics including TNF inhibitors) and biomarkers of inflammation (concentrations of leukocytes, platelets or C-reactive protein) did not correlate with the diagnosis of vitamin D deficiency." (PMID 31120977, 2019). "Vitamin D deficiency significantly enhanced the basal expression of IL-1β, IL-6, and TNF-α in the lungs of mice, while did not influence the basal expression of CXCL1 and CCL3." (PMID 24926881, 2014). "On the other hand, adjustment for resistin, IL-6, MCP-1 and TNF-α did not weaken the relationship between vitamin D deficiency and low CD4 counts." (PMID 24058636, 2013). "Furthermore, gestational vitamin D deficiency caused placental inflammation, as demonstrated by higher levels of inflammatory cytokines and chemokines, including placental TNF-α, MCP-1, and KC mRNA, in the maternal sera of subjects with vitamin D deficiency compared to controls." (PMID 41373579, 2025). "Vitamin D deficiency, independent of dietary fat, increased hepatic fat accumulation in both sexes (p = 0.003), although did not increase hepatic expression of interleukin-6 (p = 0.92) or tumor necrosis factor-α (p = 0.78)." (PMID 28880231, 2017). "Vitamin D insufficiency (HF+LVD) significantly exacerbated HF-increased serum concentrations of IL-6 and TNFα by 2.73- and 1.56-fold, respectively." (PMID 28353634, 2017). "In our studied population, no remarkable association was detected between vitamin D deficiency and inflammatory markers such as serum hs‐CRP and TNF‐α in diabetic patients with or without albuminuria." (PMID 40804707, 2025).